TNF (tumor necrosis factor)
Diseases named in the same sentence as TNF in open-access papers (continued):
Sharing a sentence is not in itself a finding about the gene and the disease.
tumor (continued). "The cytokine concentrations, especially TNF-α and IFN-γ, were significantly higher in the 118–126 peptide-stimulated T cell groups compared with non-stimulated groups (p < 0.001), demonstrating that Claudin18.2 peptide-stimulated T cells had stronger anti-tumor ability in vitro." (PMID 35681738, 2022). "Nevertheless, co-blockade of PD-L1 and TNF-α did not reduce LLC tumor growth." (PMID 35493461, 2022). "The pro and anti-tumour roles of TNF-α have largely been deduced from cancer studies, and further work on the cancer free breast may reveal the downstream impact of elevated TNF-α following fulvestrant treatment." (PMID 36347875, 2022). "Tissue-resident memory T (TRM) cells are tumor antigen-reactive TILs that produce a magnitude of cytotoxic mediators, such as granzyme B and perforin, as well as cytokines, such as interferon-gamma (IFN-γ) and tumor necrosis factor (TNF), in the tumor microenvironment (TME)." (PMID 35663939, 2022). "Overall, JMJD6 may protect tumor cells against IFN and TNF-α cytokines-mediated cell death." (PMID 35359945, 2022). "Thus, in the case of TNFR2-expressing tumor cells, TNFR2 agonists may not only improve TNF release by CD8+ T-cells, but may also sensitize the tumor cells for TNF-induced cell death." (PMID 35681583, 2022). "Moreover, the reduction of TNF-α may inhibit the transformation of Th1 to CTL, thereby reducing the ability to kill tumor cells." (PMID 36159780, 2022). "Therefore, we hypothesized that ESM1 may be a downstream molecule of TNFα that mediates bevacizumab resistance and further verified whether ESM1 was highly expressed in bevacizumab-resistant tumor tissues or cells." (PMID 36428773, 2022). "Notably, the expression level of B7–H3 was negatively correlated with the expression of CD8+T-cell activity factors TNF-α, IFN-γ, perforin, and granzyme B, which could explain why high LINC01123 expression promotes tumor immune escape." (PMID 35115487, 2022). "CcRCC cell-derived exosomes accelerate tumor growth and angiogenesis in vivo by delivering miR-27a, downregulating the expression of the tumor suppressor gene SFRP1, while increasing the expression levels of vascular endothelial growth factor and tumor necrosis factor-alpha (TNF-α)." (PMID 36620603, 2022). "Anti-tumor activity of neutrophils is regulated via various factors, such as the release of nitric oxide induced by hepatocyte growth factor (HGF) through binding to tyrosine-protein kinase MET, the generation of hydrogen peroxide (H2O2), and the secretion of the tumor necrosis factor TNF-α." (PMID 35267547, 2022). "In fact, our hypothesis about the potential role of TNFα in the impairment of barrier properties of the colon and the possible negative effect of the tumor on neighboring tissues through the production of TNFα in DMH-induced carcinogenesis was not confirmed." (PMID 36555251, 2022). "Further results of ELISA showed that the expression IL-17A and TNF-α were upregulated by YYFZBJS treatment, which suggested that YYFZBJS blocked tumor progression in CRC murine model possibly via inhibiting the accumulation of Treg cells in immune organs, and in tumor microenvironment." (PMID 36212483, 2022). "Interestingly, we found that JAK‐STAT, the well‐known IFN‐γ‐mediated signalling pathway responsible for regulating tumour PD‐L1 expression, was downregulated, whereas the PI3K/AKT, TNF, HIF‐1 and nuclear factor (NF)‐κB signalling pathways were remarkably enriched." (PMID 35696531, 2022). "Therefore, the reduction of TNF-α, COX-2, and Bcl-xL observed in our study might indicate that the treatment with HSA could modulate tumour growth and progression." (PMID 35386216, 2022). "Importantly, flow cytometry analysis of the tumors obtained after WNK463 therapy (left) revealed a dose-dependent decrease in PD-L1 levels in neoplastic cell populations but an increase in IFN-γ and TNF-α produced by CD4+ and CD8+ T cells in tumor-infiltrating lymphocytes." (PMID 36357569, 2022).
tumor (continued). "Notably, this TNFα- and IL-2-armed OV demonstrated synergy with mesothelin specific CAR T cells in a preclinical mouse model of pancreatic cancer, supported CAR T cell activity, with enhanced tumour regression and survival and prevention of metastases." (PMID 35205725, 2022). "However, TNF does not kill malignant tumor cells directly, and a local TNF injection alone is ineffective." (PMID 35844550, 2022). "Second, CAR NK cells can kill tumor cells through CAR-dependent and NK cell receptor-dependent mechanisms, such as inducing apoptosis of target cells by releasing TNF-α, inducing ADCC mediated by CD16, and activating other immune cells by producing IFN-γ, which may kill off-target tumor cells." (PMID 35432345, 2022). "Additionally, TNF-α promotes a rapid metalloproteinase-mediated TGF-α shedding from keratinocyte membrane, attributed to EGFR trans-activation and accelerated epithelial cell regeneration (epidermal hyperplasia), which aggravates skin inflammatory conditions." (PMID 36204219, 2022). "Therefore, it is likely that immune cells in hu-BLT mice are not only suppressing the tumor growth by direct lysis of the stem-like tumors, but also by differentiating the tumor cells in vivo via secretion of IFN-γ and TNF-α, which limits the growth and expansion of tumor cells." (PMID 36612108, 2022). "Additionally, the specific pDNA uptake rate and TNFα expression rate of tumor cells are not reported in the present study." (PMID 34994069, 2022). "Since accumulating evidence suggests that TNF also has the potential of promoting tumor development under certain conditions, strategies to induce apoptosis or necroptosis using various downstream inhibitors of TNF without changing proliferation are being tested." (PMID 35022391, 2022). "Furthermore, interrogation of the HIS in immune organs and tumors by flow cytometry revealed increased Granzyme B+, TNFα+ and IFNγ+ CD4+ T cells among the human tumor infiltrating leukocytes (TIL) that correlated with reduced tumor growth in the combination-treated HIS-mice." (PMID 36419897, 2022). "Tcf-1-engineered cells may primarily enact anti-tumor activity via IFN-γ, TNF-α, and FAS-ligand." (PMID 35460379, 2022). "M1 macrophages secrete pro-inflammatory cytokines such as IL-12, tumor necrosis factor (TNF)-α, CXCL-10, and interferon (IFN)-γ, and produce high levels of nitric oxide synthase (NOS), which promote inflammatory response, pathogen clearance, and anti-tumor immunity." (PMID 35965509, 2022). "Additionally, it has been demonstrated that NK and CD8+ T cells can induce pyroptosis in cancer cells that express GSDMB to promote tumor clearance via the GzmA-GSDMB axis, moreover, this process is enhanced by interferon-γ (IFN-γ) and tumor necrosis factor (TNF)." (PMID 36523974, 2022). "The detrimental consequence that may be driven by such treatments may explain the findings obtained in TNFα-/- mice that could not mount T cell-mediated anti-tumor effects." (PMID 35663982, 2022). "The release of inflammatory factors, including IL-1β, IL-1 receptor antagonist, IL-8, IL-10, and tumor necrosis factor-alpha (TNF-α) changes the adhesion of gastric mucosal cells, which leads to the migration and diffusion of tumor cells without mutations of tumor suppressor genes." (PMID 36185234, 2022). "Comparing with the control groups, treatment with URB + US not only increased the number of functional CD4+ T cells in tumor, including IFN-γ+CD4+ and TNF-α+CD4+ T cells, but also elevated the number of functional CD8+ T cells, such as IFN-γ+CD8+, TNF-α+CD8+ and GranzymeB+CD8+ T cells." (PMID 35918309, 2022). "A persistent presence of inflammatory stimuli, possibly a combination of TNF, IL1, TGFβ, high levels of fatty acids, or LPS released from gut microbiota may lead to the activation of Tak1 both in the surrounding liver and HCC and may drive tumor progression." (PMID 35053591, 2022).
tumor (continued). "In addition, inhibitors of TNF-α, which are applied in rheumatoid arthritis, have not been reported to successfully attenuate tumor-induced bone resorption." (PMID 36614130, 2022). "NK cells are capable of killing tumor cells without antigen presentation and release TNF and IFN-γ." (PMID 36611932, 2022). "Tumor-derived sEVs contain a variety of angiogenic factors, including VEGF, fibroblast growth factor (FGF), platelet-derived growth factor (PDGF), basic fibroblast growth factor (bFGF), transforming growth factor-β (TGF-β), tumor necrosis factor-α (TNF-α), and IL-8." (PMID 36499561, 2022). "In addition, ADO-A2AR is able to preclude the maturation, activation, proliferation, and cytotoxicity of natural killer (NK) cells to suppress their secretion of pro-inflammatory cytokines including IFN-γ and TNF-α, while the ablation of ADO signaling promotes NK maturation and reduces tumor growth." (PMID 35836249, 2022). "In addition, previous studies have illustrated that TNF-α inhibitors did not affect the tumor rejection." (PMID 36016934, 2022). "Moreover, many cytokines (e.g., TNF, IL-1, and IL-6) and VEGF produced as a result of neutrophil activation may increase tumor growth." (PMID 35165274, 2022). "For instance, NF-ĸB-mediated factors (TNF-α, IL-1β, IL-6, CCL2, CXCL8 and CXCL10) can protect against apoptosis, and pro-angiogenic growth factors (such as VEGF or PDGF, TGF-β and FGF) that adapt tissue architecture and support tumor cell migration, invasion and metastasis." (PMID 35707536, 2022). "Therefore, the HION@Macs could significantly increase M1‐related CD86, TNF‐α, and iNOS markers and decrease M2‐related CD206 marker, as well as, potent dendritic cells (DCs) maturation and tumor infiltration of CD8+ T cells." (PMID 37323705, 2022). "In addition to the direct cytotoxic activity of the granules containing MBP on tumor cells, eosinophils in tumor microenvironment (TME), when activated by interferon (IFN)-γ and tumor necrosis factor (TNF)-α efficiently promote mobilization of CD8+ cytotoxic T cells from circulation." (PMID 35844571, 2022). "Therefore, it will be of fundamental interest to address the question if there is a direct crosstalk between TNFα and NF-κB signaling in promoting metastasis of BCSC to the liver tissue or in the development of new blood vessels within the tumor microenvironment in metastatic liver disease." (PMID 36290384, 2022). "Cluster 6 and Cluster 3 were not adjacent, but similar tissue (tumor) activated the same pathways (Estrogen Response Early, Epithelial-Mesenchymal Transition, Allograft Rejection, Inflammatory Response, TNF-alpha Signaling via NF-kB, and Interferon Gamma Response)." (PMID 35260632, 2022). "Therefore, to test whether decreased TNF-α and increased IL-33 do indeed lead to increased numbers of CD103+ DCs in the tumor microenvironment, we stained the tumor sections for both CD11c and CD103 and observed a significant increase in both DC markers." (PMID 36256464, 2022). "The tumor microenvironment is characterized in part by inflammation, with tumor cells recruiting activated fibroblasts and immune cells which in turn secrete tissue-specific soluble factors including transforming growth factor beta (TGF-β) and tissue necrosis factor alpha (TNF-α)." (PMID 35846375, 2022). "Besides, JUB decreased TNF-α and IL-4, -6, and -10 levels in mice of groups C (tumor-bearing + JUB) and G (tumor-bearing + CUMS + JUB) as compared with the corresponding control groups B (tumor-bearing control) and F (tumor-bearing + CUMS)." (PMID 36254198, 2022). "Tnfrsf1b, one of the receptors of tumor necrosis factor (TNF), had been identified as a survival factor, which could not only maintain cell survival and enhance proliferation but also participate in the adhesion and migration of tumor cells." (PMID 36118769, 2022). "However, CAR T cells treated with anti-TNFα were not impaired in tumour killing relative to the cFLIP expressing CAR T cells." (PMID 36230780, 2022).
tumor (continued). "In addition, studies of IL-1β, IL-11, IL-17, IL-18, and TNF also indicate that proinflammatory cytokines are key regulators for TME in inhibiting tumor cell proliferation, reducing inflammation, and preventing tumor metastasis." (PMID 35069767, 2022). "In addition, minimal TGF-β and TNF-α co-expression was observed among TIL-B, suggesting that the expression of each cytokine may be mutually exclusive among the B cell tumor infiltrate." (PMID 35909944, 2022). "HCC is a well-known example of a tumor induced by inflammation, and a variety of immune and inflammatory factors, including T cells, cytokines, etc., play crucial roles in the development of HCC, including interleukin-6 (IL-6), interferon-α (TNF-α), TGF-β, and other cytokines." (PMID 36278230, 2022). "Additionally, serum levels of immunostimulatory cytokines including IFN-β, IL-6, TNF-α and IFN-γ have increased by varying degrees in 4T1 tumor (4-, 6.7-, 6-, and 4-fold) and B16F10 tumor (5-, 6.5-, 4-, and 3.2-fold) bearing mice, validating the successful induction of antitumor immune responses." (PMID 36167857, 2022). "Moreover, IL12 was only induced by the the co-culture of murlentamab-opsonized SKOV3-R2+ tumor cells with M0 while TNFα secretion was not modified." (PMID 33924378, 2021). "Because of the involvement of cancer inflammation in promoting tumor aggressiveness, we determined the impact of glycolysis and OXPHOS on the activation of p65, which is a canonical transcription factor mediating the proinflammatory activities of TNFα and IL-1β." (PMID 34072893, 2021). "However, several pro-inflammatory cytokines, including IL-1β, IL-6, and IL-17, are blocked by infliximab stimulation or combined treatment of infliximab and TNF-α, which indicates that anti-TNF-α treatment might modulate tumor-influenced inflammation in HCC." (PMID 34948424, 2021). "Furthermore, the considerably unregulated expression of TNFα, IFNγ, and CD107a was aborted in the absence of tumor cells even under the stimulation by Y111." (PMID 34040604, 2021). "However, the source of TNFα upon STING activation remains unknown, and it is unclear why STING activation triggers apoptosis specifically to tumour ECs." (PMID 34285232, 2021). "Recently, we have investigated the anti-tumor effects of birinapant in HPV(−) HNSCC cells, and observed that cells retaining FADD/BIRC2 amplification and overexpression were sensitive to birinapant, and the effects were enhanced by death agonists TNFα or TRAIL23." (PMID 33737574, 2021). "The survival benefit was accompanied by a significant infiltration of IFNγ-, Granzyme B-, and TNFα-secreting effector T-cells, demonstrating that the combined use of CD40 agonist and PD1 antagonist antibodies can reprogram immune resistant tumors in favor of anti-tumor immunity." (PMID 34201127, 2021). "Prospectively, a combination of inflammatory factors (such as TNF-α) and adhesion molecules (such as ICAM1 and ALCAM) neutralizing antibodies might be a useful adjuvant therapy to prevent tumor metastasis in the process of tumor treatment." (PMID 34222020, 2021). "Antigen-specific CD8+T cells may infiltrate the tumor and represent the major effector T lymphocytes able to kill cancer cells by granule exocytosis, Fas ligand (FasL)-mediated apoptosis and by secreting interferon (IFN)-γ and tumor necrosis factor (TNF)-α." (PMID 33920505, 2021). "Considering the accumulation of pre-clinical data on the role of TNFR2 and clinical reports of TNFR2+ Tregs and tumor cells in cancer patients, it is now clear that a TNFR2-centered approach could be a viable strategy, once again making the TNF-α pathway a promising anti-cancer target." (PMID 34712661, 2021). "In addition, KEGG pathway results showed that 323 genes were primarily enriched in TNF signal path, JAK-STAT signal path, and Toll-like receptor signal path, suggesting CYP1B1-AS1 may be involved in tumor progression of GBM." (PMID 35003394, 2021).
tumor (continued). "One study found that inducible IL-12 allowed CAR T cells to eradicate antigen-positive tumor cells and prevent outgrowth of antigen negative tumor cells by recruiting and activating macrophages to produce TNFα and upregulate costimulatory molecules CD80/CD86 to enhance T cell responses." (PMID 34177932, 2021). "However, the increased tumor development seen in Zfp36ΔEP mice did not require keratinocyte-derived TNF production, indicating that TTP controls other pathways that play dominant roles in this model of tumorigenesis." (PMID 33497366, 2021). "In tumor immunity, M1 macrophages produce inflammatory cytokines such as tumor necrosis factor α (TNF-α), IL-6 and IL-12, and exert an anti-tumor effect, whereas M2 macrophages produce immunosuppressive cytokines such as IL-10 and TGF-β, and inhibit anti-tumor immune reactions." (PMID 34359568, 2021). "The high levels of TNF-α, the accumulation of receptor-interacting protein kinase-3 (RIP3K) and its lack of cleavage by Caspase-8 in mice injected with HepG2/SB3 provide evidence of necroptotic death in this experimental model, highlighting its protective function in slowing down tumor growth." (PMID 33922660, 2021). "Notably, tumor-infiltrating lymphocytes (TILs) isolated from act-A-treated mice secreted higher levels of the typical effector cytokines IFN-γ and TNF-α and lower levels of the immunosuppressive cytokine IL-10 upon ex vivo antigenic stimulation compared to untreated mice." (PMID 34548096, 2021). "Anti-hPVRIG mAb significantly enhanced the cytokine secretion (IFN-γ and TNF-α) and degranulation (CD107a) of NK cells from PBMCs in co-culture with SW620 cells and significantly improved the cytotoxicity of purified NK cells against SW620 tumor cells at indicated effector/target ratios in vitro." (PMID 34174928, 2021). "Of note, the simultaneous in situ detection of the corresponding genes, TNFRSF9, TNF, and IFNG, could represent a rapid and effective strategy for the identification and future functional characterization of the majority of the tumor-specific reactive TIL repertoire in scRNAseq data." (PMID 34707600, 2021). "Recently, an interesting study demonstrated that potent pro-inflammatory cytokines, such as tumor necrosis factor (TNFα) and interleukin-1β (IL-1β), that are present in the TME of breast primary tumors, may lead to the conversion of mesenchymal stem cells to tumor-promoting inflammatory CAFs." (PMID 34885027, 2021). "Moreover, TNF is a proinflammatory cytokine secreted by macrophages, T-lymphocytes and mastocytes, inducing an overexpression of MMP-2, MMP-3, MMP-7 and MMP-9 in the tumor microenvironment, contributing to the invasive capacity of malignant cells." (PMID 34204372, 2021). "The results showed that IL-2, IL-12, IL-17, TNF-α, and INF-Υ, which were immunity promoting cytokines, were significantly upregulated in drug serum, while IL-10, TGF-β, VEGF, and MMP-9, which were immunity abating or tumor promoting proteins, were significantly downregulated in drug serum." (PMID 33505491, 2021). "Interestingly, ELAVL1 (HuR) was shown to modulate the expression of IL-5, IL-6, CCL-5, and TNF-alpha cytokines harboring the HuR-binding motif, which in consequence can influence the cross-talk between HRS cells and the immune infiltration in the tumor microenvironment." (PMID 33544339, 2021). "However, external administration of TNFα was shown to occupy TNFR1 expressed by tumor and healthy endothelial cells without toxicity towards the latter, due to the presence of a low number of receptors on healthy cells." (PMID 34445397, 2021). "Additionally, through promoting the secretion of tumor necrosis factor-α (TNF-α) and interferon γ (IFN-γ), metformin could significantly boost the anti-tumor activity of CD8+ T cells to indirectly retard tumor progression." (PMID 34572586, 2021).